ETV1 (ETS variant transcription factor 1)
Diseases named in the same sentence as ETV1 in open-access papers (continued):
Sharing a sentence is not in itself a finding about the gene and the disease.
tumor (105 papers, 2005 to 2025). "In UF PCa, ETV1 overexpression was related to pT3 tumor stage (p = 0.031), and ERG overexpression was associated with perineural infiltration (p = 0.044), the latter also showing a trend to be related to younger patients (p = 0.058)." (PMID 38017230, 2024). "Fusion of the ETS gene results in the high expression of ERG or ETV1, and it is an important cause of prostate tumorigenesis and tumor development." (PMID 36289913, 2022). "Particularly, in both cohorts, increased ETV1 expression was significantly correlated with loss of tumor encapsulation, poor tumor differentiation, microvascular invasion, as well as advanced tumor nodular metastasis (TNM) stage." (PMID 36109787, 2022). "Third, the multivariate analysis showed that ETV1 expression, in addition to conventional risk factors, such as tumor size, location and mitotic count, was an independent factor of recurrence." (PMID 32901065, 2020). "But also in prostate models due to inhibition of ERG and ETV1, YK-4-279 results in a decrease of the expression of the ERG-target genes PLAU, PLAT and ADAM10 and ETV1-target gene MMP13 associated with in vivo anti-tumor activities." (PMID 29921764, 2018). "It was discovered that TMPRSS2 is fused to either ERG or ETS variant 1 (ETV1) and this frequent event contributes to PCa tumour progression." (PMID 27891254, 2016). "ETV1 expression was significantly correlated with the primary tumor location tumor size, and Miettinen’s risk classification (p <0.05, Fisher’s exact test)." (PMID 23977394, 2013). "There was a significant association between PTEN score and ERG/ETV1 status (P<0.001) with 66% of PTEN loss tumours also having an ERG/ETV1 gene rearrangement compared with 34% of normal PTEN tumours." (PMID 20104229, 2010). "Moreover, we showed in a model of human HGF knock‐in mice that the pro‐tumour property of ETV1/ERG factors is closely linked to MET activity and proposed a specific molecular signature of this cooperation after conducting a large‐scale transcriptomic analysis." (PMID 39374163, 2025). "Following a series of in vitro and in vivo experiments, the authors proposed a paradigm in which ectopic SUMO‐conjugated Etv1 re‐establishes tumor‐initiating capacities in a SUMOylation‐deficient context but leaves tumor cells in a low‐cycling/quiescent state, akin to the CSC phenotype." (PMID 40546087, 2025). "SUMO1, Uba2, and Ubc9 upregulation in PCs could lead to enhanced SUMOylation of the TF ETS variant 1 (ETV1), and blocking ETV1 tumor-promoting activity by SUMOylation could suppress the growth of PC." (PMID 35465332, 2022). "Additionally, the correlation between the expression of ETV1 and the marker genes of immune cells (ICs) implicated the role of ETV1 in regulating tumor immunology." (PMID 35860243, 2022). "Remarkably, the small molecule YK-4-279 effectively inhibited ERG- and ETV1-driven transcriptional activity, leading to decreased cell motility and invasion and reduced primary tumor growth and metastasis of fusion-positive PC xenografts." (PMID 40427154, 2025). "By using a specific MET tyrosine kinase inhibitor in a humanised hepatocyte growth factor (HGF) mouse model, we also establish that MET activity is required for ETV1/ERG‐mediated tumour growth." (PMID 39374163, 2025). "Several miRNAs, including miR-129-5p and miR-17-5p, are proved to mitigate tumor development by targeting ETV1." (PMID 38730434, 2024). "Consistent with RCC tumor tissues, miR-22-3p expression was down-regulated and ETV1 levels were augmented in RCC cells compared with normal HK2 cells." (PMID 38730434, 2024). "By combining these experiments in vitro and in vivo, this study has led to the identification of circPRELID2 silencing that can exert an anti-tumor function in RCC via the miR-22-3p/ETV1 cascade." (PMID 38730434, 2024). "We compared ETV1 expression in our cohort and found that ETV1 are upregulated in GIST tissues of patients with liver metastasis compared with corresponding non-tumor tissue." (PMID 36911388, 2023).
tumor (continued). "Overexpression of ETV1 in various tumors mediates cell growth, invasion, and migration in various tumor cells, leading to tumor progression, metastasis, and drug resistance." (PMID 37197420, 2023). "We found that miR-410 expression depends upon the tumor subtype, with those with ERG fusion, ETV1 fusion and SPOP mutations having a lower miR-410 expression as compared to other subtypes." (PMID 38201476, 2023). "ETV1 can bind many target genes that play a key role in regulating differentiation, proliferation, and tumor metastasis by regulating the expression of target genes." (PMID 36062065, 2022). "ETV1 binds to many target genes and plays a role in tumor progression and metastasis by regulating expression of them." (PMID 36109787, 2022). "In concordance with our data, ETV1 was upregulated in tumor tissues, and the high ETV1 mRNA level was correlated with poor survival for patients with HCC in TCGA." (PMID 36109787, 2022). "Of interest, activation of fibroblasts by either FGF2 or TGF-β was shown to induce different tumor-promoting CAF populations, a process regulated via the transcription factor ETS Variant Transcription Factor 1 (ETV1)." (PMID 35892828, 2022). "Collectively, we have uncovered a molecular subset of PCa defined by a co-deletion of CIC and ERF and further demonstrate a mechanism-based strategy to potentially limit tumor progression through ETV1 inhibition in this subset of human PCa." (PMID 36383412, 2022). "Functionally, ETV1 influences tumor progression by inducing EMT, promoting cell migration and invasion, regulating cell cycle and apoptosis, as well as mediating chemotherapy resistance." (PMID 36109787, 2022). "YK-4-279, inhibitor of ETV1, suppressed primary tumor development and metastasis in fusion positive mice with prostate cancer." (PMID 33967600, 2021). "The multivariate analysis showed that low ETV1 expression, as well as tumor size and mitotic index, was an independent factor of recurrence (hazard ratio: 8.1)." (PMID 32901065, 2020). "Even so, we have carefully examined the adenocarcinomas in order to reveal any tumor budding-related special ETV1 expression pattern as the EMT is a key feature of the tumor budding." (PMID 33335133, 2020). "But we found a significantly reduced ETV1 expression in the tumor cells of synchronous GISTs in comparison with the ICCs of the adjacent gastric wall." (PMID 33335133, 2020). "Other than ERG fusions, we observed nine tumors with ETV1 rearrangements (10%) and 1 tumor with an ETV5 fusion transcript (1%)." (PMID 30464211, 2018). "Forced expression of miR-17-5p in MDA-MB-231 or BT549 cells significantly decreased ETV1 expression and suppressed cell proliferation, migration in vitro and tumour metastasis in vivo." (PMID 29126392, 2017). "Although ERG and ETV1 were assayed on separate TMA slides, at least one of these two tumors expressed ERG and ETV1 expression in apparently separate subsets of tumor cells, suggesting a potential collision between two independent clones." (PMID 28186998, 2017). "In 79 ETV1-positive tumours, miR-17-5p-high expression cases had significantly higher survival rates than patients with miR-17-5p-low expression (log-rank test, P < 0.001)." (PMID 29126392, 2017). "ETV1 appears to be a lineage survival factor in GIST as it is involved in tumor initiation and proliferation." (PMID 29371979, 2017). "The current study showed that miR-17-5p functions as a tumour suppressor by targeting ETV1 in TNBC progression and metastasis and is a independent favourable predictor for TNBC patients’ prognoses." (PMID 29126392, 2017). "Either ETV1 or COP1 expression status was significantly associated with TNM stages of TNBC, the number of lymph nodes involved and tumor relapse." (PMID 25884720, 2015). "It's worth noting that ETV4, a homologue of ETV1, was elevated in colorectal cancer tissues and enhanced tumor invasion." (PMID 26356816, 2015).
tumor (continued). "In the first tumor 5′-RACE on cDNA showed linkage of the complete ETV1 transcript to the first exon of a prostate-specific two exon ncRNA gene that maps on chromosome 14 (EST14)." (PMID 21298110, 2011). "Gleason grades of these tumours demonstrate that in 21% of the normal ERG/ETV1 and PTEN loss tumours, Gleason grade was <7 supporting a reclassification of this low Gleason grade patient subgroup." (PMID 20104229, 2010). "As we found these partners to only account for ∼34% of all ETV1 translocation events, we undertook 5′-RACE studies to identify novel ETV1 fusion partners in our paraffin-embedded tumour samples." (PMID 18594527, 2008). "We constructed a TMA block containing cores from all of the cancers harbouring ETV1 re-arrangements (23 tumours) and six randomly selected cancers with an ERG gene rearrangement." (PMID 18594527, 2008). "The tumor inhibition rate was analyzed and the tumor inhibition rates in the si-KIFC and si-KIFC+Ov-NC groups were significantly higher than those in the si-NC mice (p < 0.05), whereas ETV1 overexpression reduced the tumor inhibition rates induced by si-KIFC1 (p < 0.05)." (PMID 40612867, 2025). "From the tumours, we extracted RNA and verified the expression of ETV1, ERG and MET using RT‐qPCR." (PMID 39374163, 2025). "This suggests that lncRNA TCONS_00251376 might promote the proliferation, migration, and invasion of tumor cells by upregulating the expression of ETV1." (PMID 39668941, 2025). "The up-regulation of the Cyclin D2 (CCND2) and the ETS Variant Transcription Factor 1 (ETV1), whose dysregulation may trigger initiation and progression of multiple types of tumours was also highlighted." (PMID 38528259, 2024). "In two HCC patient cohorts (cohort I, n = 260; cohort II, n = 280), ETV1 expression was correlated with PTK2 and c-MET expression, and elevated expression of PTK2 or c-MET was associated with poor tumor differentiation, microvascular invasion, loss of encapsulation, and advanced TNM stage." (PMID 36109787, 2022). "Moreover, we detected the serum HGF levels in the HCC patients by ELISA and detected the ETV1 levels in the tumor tissues of HCC patients by IHC." (PMID 36109787, 2022). "Negative regulation of ETV1 can activate COP1 as a tumor suppressor in patients with TNBC." (PMID 34746770, 2021). "In summary, our results showed that silencing GRP94 caused reduced tumor progression, invasion, metastasis, and EMT reverse, and down-regulated the expression of ETV1 through inhibition of MAPKs which play a pivotal role in cell proliferation and differentiation." (PMID 33967600, 2021). "No tumor budding associated special expression pattern of the ETV1 was observed in the adenocarcinomas." (PMID 33335133, 2020). "The expression of ETV1 is higher within tumor cells compared with normal tissues." (PMID 32686362, 2020). "Accordingly, one can speculate that the ETV1 expression level should be lower in the budding tumor cells of the invasion front." (PMID 33335133, 2020). "A similar reduction could be detected for Bmi1 and Etv1, the latter as one of the possible driving forces in tumor development in this particular tumor model." (PMID 32373532, 2020). "These bioinformatics results implicate that SMAD2, SMAD3 and SMAD4 may exert tumor suppressive functions in the prostate, including the inhibition of ETV1’s oncogenic activity." (PMID 31160676, 2019). "This demonstrated that the 3′-end of ETV1 was overexpressed in 5% (5/106) of the tumor samples." (PMID 31537872, 2019). "Up-regulation of miR-17 in GIST cell lines inhibits cell proliferation by degrading ETV1 mRNA, which may suppress the tumour progression." (PMID 29126392, 2017). "Kaplan–Meier curves and log-rank test showed that women in the miR-17-5p-low expression group (n = 82) had a shorter overall survival (OS) time than those in the miR-17-5p-high expression group (n = 23) (log-rank test, P < 0.001), which was consistent with ETV1-positive tumour group." (PMID 29126392, 2017).
tumor (continued). "Our data indicate that miR-17-5p acts as a tumour suppressor in TNBC by targeting ETV1, and a low-abundance of miR-17-5p may be involved in the pathogenesis of TNBC." (PMID 29126392, 2017). "Age, tumor size and pathological types had not been found to be associated with ETV1 or COP1 expression status." (PMID 25884720, 2015). "The results support the hypothesis that COP1 might play a role in tumor suppression by degrading or ubiquitinating multiple substrates, besides ETV1." (PMID 25884720, 2015). "In conclusion, we demonstrated that COP1 might be a tumor suppressor by negatively regulating ETV1 in patients with TNBC." (PMID 25884720, 2015). "Immunohistochemistry revealed that ETV1 was diffusely localized in the nuclei of the tumor cells." (PMID 23977394, 2013). "To identify tumours with translocation of ETV1 to the androgen-regulated prostate-specific region at 14q13.3–14q21.1 we co-hybridised a TMA slice with a 3′-ETV1 FISH probe (red) and a FISH probe consisting of six BACs spanning the entire region of 14q13.3–q21.1 (green)." (PMID 18594527, 2008). "Our aim was to analyze the protein expression of PTEN, SPOP, SLC45A3, ETV1, ERG and the “triple hit” (ERG overexpression, PTEN plus SLC45A3 loss) in unifocal (UF) and MF PCa, to evaluate their value as prognostic markers according to focality, and the role of tumor heterogeneity in MF disease." (PMID 38017230, 2024). "MIPOL1 is thought to act as a tumor suppressor, and its fusions may accompany ETV1 fusions." (PMID 37349736, 2023). "Next, we examined whether ETV1 is responsible for tumor growth and metastasis in vivo." (PMID 36109787, 2022). "However, as elevated expression levels of ETV1 are detected in multiple tumor types and can lead to increased invasiveness of tumor cells, this might also be the oncogenic mechanisms of these fusions." (PMID 35169893, 2022). "This patient's tumor demonstrated 8 mutations overall including alterations in the PI3K, MAPK pathways (mutations in FBXW7, FGFR1) with concurrent epigenetic and transcriptional deregulation, specifically ARID1A, ETV1 rearrangement, NOTCH1 APIP-NOTCH1 fusion, and MYST3 amplification." (PMID 28781987, 2017). "Considering the absence of an overlap between ETV1 target genes in vitro and in vivo, we questioned whether we could use the observed impact of ETV1 and ETV4 silencing in invasion and AIG to find phenotype-associated genes that could be useful as markers of tumor aggressiveness in vivo." (PMID 25595908, 2015). "COP1 might be a tumor suppressor by negative regulating ETV1 in patients with TNBCs." (PMID 25884720, 2015). "The tumor size after KIFC knockdown was lower than that in the si-NC group, whereas ETV1 overexpression increased the tumor size induced by si-KIFC." (PMID 40612867, 2025). "We compared the expression levels of ETV1, ETV4 and ETV5 mRNA between the non‐tumour brain samples and GBM samples from the TCGA and Rembrandt databases." (PMID 40275610, 2025). "We performed subcutaneous injection of PC3M Ctrl, ETV1 and ERG cells into both flanks of the mice and monitored tumour growth over one month." (PMID 39374163, 2025). "To investigate the involvement of ETV1, ERG and MET in pro‐tumour capacities and the effect of their concomitant activity, we assessed migration and invasion using Boyden chamber assays, comparing all cell lines." (PMID 39374163, 2025). "ETV1, ETV4, and ETV5 can enhance the proliferation, migration, and invasion of tumor cells, thereby leading to tumor progression, metastasis, and drug resistance." (PMID 39668941, 2025).
tumor (continued). "Subcutaneous injection of cells from the PC3M model demonstrated that overexpression of ETV1 and ERG induced greater tumour growth than control cells throughout the evaluation process." (PMID 39374163, 2025). "By contrast, in UF PCa, only the overexpression of ETV1 and ERG were related to high tumor stage and perineural infiltration, respectively." (PMID 38017230, 2024). "In the setting of Pten deletion that by itself robustly mediates neoplasia in the mouse prostate, ERG and ETV1 overexpression reproducibly promotes cancer progression in numerous studies." (PMID 37018402, 2023). "ETV1, ETV4, and ETV5 comprise the PEA3 transcription factor subfamily and were found to be significantly related to numerous tumor markers." (PMID 35860243, 2022). "BRAF mutants generally activate MEK/MAPK and regulate the downstream factor ETV1, thereby promoting ICC proliferation and transformation into a tumor." (PMID 36497489, 2022). "We explored the correlation of ETV1, ETV4, and ETV5 with tumor-infiltrating immune cells (TIICs) in CRC tumor microenvironments via the Tumor Immune Estimation Resource (TIMER) and Gene Expression Profiling Interactive Analysis (GEPIA)." (PMID 35860243, 2022). "Overexpression of ETV1, combined with oncogenic NRAS (G12D), can transform primary melanocytes and promote tumor formation in mice." (PMID 33424867, 2020). "Altogether, these data provide more insights into the regulation and action of ETV1 and additionally suggest that TGF-β/SMAD signaling exerts its tumor suppressive activity, at least in part, by curtailing the oncogenic potential of ETV1 in prostatic lesions." (PMID 31160676, 2019). "In the present study, an inverse expression pattern of miR-17-5p and ETV1 in TNBC cell lines and tumour tissues was detected." (PMID 29126392, 2017). "ETV1 was closely related to TNM stage (P < 0.05), lymph nodes involved (P < 0.05) and tumour relapse (P < 0.01)." (PMID 29126392, 2017). "For example, in PRAD, the most commonly found tumor subgroup has gene fusions involving members of the E26 transformation-specific (ETS) family of TFs, such as ERG, ETV1, ETV4, and FLI1." (PMID 27833659, 2016). "We found that ETV1-positive expression was significantly correlated with TNM stages of TNBCs, lymph node metastasis and tumor relapse." (PMID 25884720, 2015). "Treatment with Capmatinib administered to mice during experimentation reduced the tumour growth capacity of PC3M cells overexpressing ETV1 as ERG, whereas the effect was not significant on control cells." (PMID 39374163, 2025). "We therefore proposed that MET may be a relay in the expression of the ETV1 and ERG genes in hormone‐independent stages, leading to significant tumour capacity." (PMID 39374163, 2025). "Furthermore, the tF-1 tumor subtype has more frequent ETS family gene fusions (such as ERG and ETV1) than the tF-2 tumor subtype." (PMID 36661724, 2023). "Since BRD32048 was previously shown to decrease invasiveness in ETV1-fusion positive PCa cells (LNCaP), but not significantly impact tumor cell viability, we unexpectedly observed that silencing CIC in DU-145 cells mildly enhanced sensitivity to BRD32048." (PMID 36383412, 2022). "Notably, in PCa, CIC is commonly altered through genomic loss (homozygous and heterozygous deletion) in ~10% of PCa patients and inactivation of CIC de-represses ETV1, ETV4, and ETV5 transcription to promote tumor progression." (PMID 36383412, 2022). "Moreover, we investigated the correlation of ETV1 and ETV5 with tumor-infiltrating immune cells (TIICs) in CRC tumor microenvironments via the Tumor Immune Estimation Resource (TIMER) and Gene Expression Profiling Interactive Analysis (GEPIA)." (PMID 35860243, 2022). "The EWS tumours analysed in this study had EWS translocations with FLI1 (n = 3) and ETV1 (n = 2)." (PMID 34471258, 2022).